IGF1R (insulin like growth factor 1 receptor)
Diseases named in the same sentence as IGF1R in open-access papers (continued):
Sharing a sentence is not in itself a finding about the gene and the disease.
lung cancer (continued). "For instance, genetic silencing of FURIN inhibits processing of the insulin-like growth factor 1 receptor (IGF1R), migration, and invasion in lung cancers, which indicates that furin is a potential therapeutic target in lung cancers." (PMID 33968987, 2021). "In human lung cancer, the tumor microenvironment harbors abundant CAFs that secrete IGF-II, a signaling molecule that binds to IGF1R on lung CSCs to activate Akt/Nanog cascades, which play crucial roles in maintaining lung cancer stemness." (PMID 33407730, 2021). "Here the authors show that glucocorticoid receptor activation induces cancer cell dormancy in lung cancer by regulating CDKN1C expression through a distal enhancer, and these dormant cells are addicted to IGF-1R signalling pathway." (PMID 34272384, 2021). "To investigate interactions between miRNA and mRNA with circ‐IGF1R, we used RNA‐seq for lung cancer PC9 and A549 cell lines overexpressing circ‐IGF1R, and their corresponding normal cell lines." (PMID 32107851, 2020). "Together with findings that osimertinib increased the IGF-1R protein level, these results strongly suggest that an increased amount of IGF-1R, which maintains the association with EGFR and Gab1, may restore survival signals in AXL-low-expressing EGFR-mutated lung cancer cells exposed to osimertinib." (PMID 32929081, 2020). "The potential network of circ‐IGF1R–miR‐1270–VANGL2 was preliminarily determined, and the expression patterns of miR‐1270 and VANGL2 were verified in lung cancer cell lines." (PMID 32107851, 2020). "Among these, PROTACs 12a and 12b were capable of inducing the degradation of both IGF-1R and Src proteins at 1–5 μM in the MCF7 (human breast cancer) and A549 (human lung cancer) cells." (PMID 32340152, 2020). "In the present study, we first assessed the expression and biological function of circ‐IGF1R in NSCLC tissues and cells, and we performed RNA‐seq in lung cancer cell lines overexpressing circ‐IGF1R to further explore its mechanism of action." (PMID 32107851, 2020). "In non–small-cell lung cancer (NSCLC), the IGF-1R/Tescalcin/c-Src complex mediates the STAT3 pathway to induce ALDH1 expression, which preserves CSC features." (PMID 33511137, 2020). "Thus, IGFBP7 may be a novel target for blocking IGF-1R signaling in lung cancer cells." (PMID 30609749, 2019). "The insulin-like growth factor (IGF) system, involving two hormones of IGF-1 and IGF-2, two receptors to these two hormones (IGF-1R and IGF-2R), and several binding proteins (IGFBP1-7), plays an important role in the development of lung cancer." (PMID 31354621, 2019). "Alterations in these four target genes were then explored in 4105 lung cancer patients, and BCL2L1 and IGF1R were demonstrated to be aberrantly expressed." (PMID 30497474, 2018). "Further, more lung cancer patients with higher levels of all three molecules (GRB10, IRS1, and IGF1R) were in stage III/IV group than the stage I/II group." (PMID 29973593, 2018). "Thus, Src appears to exert mutant KRAS-driven events as its downstream effector, and considering our previous finding demonstrating the involvement of IGF1R activation in the development of lung cancer, co-targeting IGF1R and Src may halt the progression of mutant KRAS-driven lung tumor development." (PMID 29455661, 2018). "Expression and alterations of BCL2L1, IGF1R, MAPK8, and FAS were investigated in lung cancer using TCGA database, and 4105 clinical samples provided by 13 studies were utilized in this study." (PMID 30497474, 2018). "Heterodimerization between IGF1R and epidermal growth factor receptor (EGFR) mediates the activation of bypass signaling, leading to resistance to gefitinib and erlotinib in lung cancer." (PMID 29455661, 2018). "In the top 50 potential lung cancer-related miRNAs, miR-133a plays a tumor suppressor role in non-small cell lung cancer (NSCLC) by targeting IGF-1R, TGFBR1 and EGFR." (PMID 29498680, 2018).
lung cancer (continued). "NF-κB has been identified as a critical mediator of EMT in cancer progression and IGF1R pathway has been reported to be involved in EGFR TKI resistance and induction of EMT in lung cancer." (PMID 29190911, 2017). "Lung cancer stem cells (LCSCs) are responsible for the initiation, progression, metastasis and relapse of lung cancers (e.g. SP+ LCSCs, CD24+IGF1R+ LCSCs and CD133+ LCSCs)." (PMID 28977934, 2017). "Previously, PPP was shown to decrease the phosphorylation of IGF1R downstream pathways, MAPK and Akt in lung cancer, Ewing sarcomas and glioblastomas." (PMID 28793874, 2017). "However, clinical and pre-clinical studies have revealed that TKI resistance is a transient event and may be reversed by the long-term culture of TKI-resistant lung cancer cells in TKI-free medium or by treatment with inhibitors of insulin-like growth factor 1 receptor or chromatin-modifying agents." (PMID 28683123, 2017). "More importantly, proliferation index of lung cancer cells, SP+ LCSCs ratio and CD24+IGF1R+ LCSCs ratio in CTX+SHSB group were remarkably lower than that in control and CTX groups." (PMID 28977934, 2017). "In lung cancer, miR-486 regulates the insulin growth factor signaling pathway by targeting insulin-like growth factor 1 (IGF1), IGF1 receptor (IGF1R), and phosphoinositide-3-kinase, regulatory subunit 1 (alpha) (PIK3R1)." (PMID 26966540, 2015). "Previous studies showed that activation of IGF1R is involved in EGFR-TKIs resistance in NSCLC cell lines and in lung cancer patients." (PMID 26554308, 2015). "Despite promising preclinical data and a strong rationale for targeting IGF1R, clinical efficacy with anti-IGF1R mabs as single agents or in combination with chemotherapy has been disappointing in EWS, lung cancer and other diseases." (PMID 26173023, 2015). "In a recent study, IGF-1R was shown to be a critical and important driver for EMT related events in lung cancer." (PMID 24809702, 2014). "MiR-133a can inhibit cell invasiveness and cell growth through suppressing the expressions of IGF-1R, TGFBR1 and EGFR, which then influences the downstream signaling in lung cancer cell lines." (PMID 24816813, 2014). "Overexpression of TM4SF4 in lung cancer cells increased phosphorylation of IGF1R and activated signaling components of the PI3K pathway, the most important signaling pathway in lung cancer cells, including PI3K, AKT, and NK-kappaB." (PMID 25344917, 2014). "In these lung cancer cells, TM4SF4 overexpression increased the expression of IGF1, a ligand that activates IGF1R, which appears to be a key event in activation of the IGF1R pathway." (PMID 25344917, 2014). "EGFR-independent upregulation of pAKT by hypoxia has also been observed in lung cancer cells, whereby activation of AKT was induced via the IGF1R/PI3K/AKT pathway." (PMID 23046567, 2012). "Numerous studies have shown that dual inhibition of IGF-1R and EGFR can be synergistic in moderating growth and migration of prostate cancer, lung cancer, and colorectal cancer." (PMID 24212944, 2011). "Furthermore, lactate-induced lactylation of insulin-like growth factor 1 receptor (IGF1R) increases its protein stability and promotes its binding to IGF1, which accelerates lung cancer proliferation." (PMID 40589733, 2025). "Furthermore, other targeted drugs, such as IGF-1R inhibitors and AMPK activators, have demonstrated potential in modulating insulin resistance and lung cancer." (PMID 38449844, 2024). "Overall, the IGF-1R signaling pathway plays a crucial role in the cellular development of anti-cancer drug resistance, and the use of IGF-1R inhibitors in conjunction with other therapies offers a promising direction for lung cancer treatment." (PMID 38540176, 2024). "Kaplan‒Meier curves demonstrated that high IGF1R mRNA expression was correlated with poor first progression survival and overall survival but not postprogression survival in patients with lung cancer." (PMID 38200153, 2024).
lung cancer (continued). "Furthermore, lung cancer patients with both elevated lnc-MLETA1 and EGFR or IGF1R displayed the worst survival, indicating the superior prognostic value of combining the two parameters compared with one gene alone." (PMID 37880793, 2023). "The elevation of IGF-I and IGF-1R and their resultant interaction appears to up-regulate the PI3K/AKT/NF-κB pathway with the concomitant activation of ZEB2 and SNAIL1, altering protein expression and the EMT phenotype in certain lung cancers." (PMID 35198099, 2022). "Using lung cancer cellular models, IGF1/IGF1R signaling was related to chemo- and radio-resistance." (PMID 36224313, 2022). "Lung cancer tissue contains differential expression of multiple molecules within the IGF axis, including the boosted production of IGF-I, IGF-II, and IGF-1 receptor (IGF-1R) and decreased expression of IGF binding protein-3 (IGFBP-3)." (PMID 35198099, 2022). "Interestingly, the IGF axis is a complex molecular network (including peptide‐ligands IGF1, IGF2, and insulin, and the receptors IGF1R, IGF2R, and INSR) that is involved in a wide variety of neoplasms such as prostate, breast, colorectal, and lung cancers." (PMID 34668636, 2022). "Moreover, combined insulin-like growth factor 1 receptor (IGF1R) and MEK blockade showed significant effects in KRAS-mutant lung cancer cells and in KRAS-driven mice tumor models." (PMID 34301278, 2021). "Except the 1+ lung cancer SBC5 and the gastric cancer IGF-1R-Hs746T animal models, all the other animal models observed potent tumor regression even in the docetaxel-resistant MCF-7 tumor model, showing that W0101 was an IGF-1R dependent and effective compound for cancer therapy." (PMID 34203870, 2021). "In lung cancer cells, IGFBP2 induces erlotinib resistance by activating IGF-1R signaling." (PMID 34349753, 2021). "The expression level of circ‐IGF1R was notably lower in lung cancer tissues and lung cancer cell lines than in the adjacent normal tissues and cells (P < 0.0001)." (PMID 32107851, 2020). "It was revealed that circ‐IGF1R not only affects HCC through PI3K‐AKT‐mTOR, but also may promote the growth and metastasis of lung cancer through PI3K‐AKT‐mTOR." (PMID 32107851, 2020). "This strategy has been successful in vitro and in vivo in targeting the Ras/MAPK, EGFR, and IGF-1R kinases in ALK fusion-positive lung cancer, but is not yet applied in the clinic." (PMID 30813562, 2019). "Tea is widely consumed in both Western and Asian countries and several mechanisms have been proposed for its anti-tumor effect, including its inhibition of c-Jun and ERK1/2 in lung cancer, phospho-Akt and nuclear β-catenin levels in colon cancer, and IGF/IGF-1R axis in colon and prostate cancer." (PMID 30893904, 2019). "In accordance with previous studies, activation of IGF1R contributed to the resistance of radiotherapy in lung cancer cells; however, no data on BCL2L1 expression in LA or LSC is yet available to our knowledge." (PMID 30497474, 2018). "The expression of exosomal let-7a-5p was detected in pneumoconiosis, and all potential target genes related to exosomal let-7a-5p were predicted, among which four target genes related to lung cancer were selected for downstream analysis, including BCL2L1, IGF1R, MAPK8, and FAS." (PMID 30497474, 2018). "Also, the ERK1 checkpoint in the downstream of EGFR and IGF1R is inactivated by miR-140-3p, leading to a reduction of active AP-1 proteins including FOS and c-JUN, thus modulate invasion and transformation of lung cancer cells." (PMID 30559931, 2018). "Interestingly, few studies have shown that IGF1R pathway is also involved in the acquisition of EMT phenotype in some types of cancer cells, such as prostate cancer, breast cancer and lung cancer." (PMID 29190911, 2017). "Data from lung cancer cell lines suggest that SALL4 downregulation may result in degradation of EGFR and IGF1R proteins, possibly in part through CBL-B." (PMID 27705911, 2016).
lung cancer (continued). "In lung cancer stem cells, EFEMP1 could suppress invasion and migration of lung adenocarcinoma cells by modulating the IGF1R/PI3K/AKT/GSK3β pathway." (PMID 27351229, 2016). "Finally, we have developed an in vitro mimicry assay by co-culturing several lung cancer cell lines with various expression levels of HER1, HER3, IGF1R and cMet to address heterogeneous expression of RTKs within tumors." (PMID 27578890, 2016). "Because previous studies have reported a potential role of IGF-1R pathways in lung cancer, we analyzed the expression of phospho-IGF-1R and IGF-1R in NSCLC biopsy samples using two large repositories of tissues annotated for relevant histological and clinical variables." (PMID 25944691, 2015). "For example, gefitinib only partially blocks EGFR activity in A549 lung cancer cells, accompanied by a dramatic increase in the activity but not the expression of IGF-1R." (PMID 22545054, 2012). "A requirement for the IGF-1 receptor in mediating lung cancer growth is consistent with other reports that IGF-1 stimulates rapid anchorage-independent growth in vitro, while IGF-1R inhibition slows tumor growth in both animal xenograft studies and human clinical trials." (PMID 21699731, 2011). "Thus, there is a strong rational for dual targeting of IGF-1R and ErbB2 or EGFR in breast or other carcinomas such as lung cancer." (PMID 24212944, 2011). "In addition, the IGF1R-mediated activation of PI3K leads to an acquired resistance to gefitinib, an epidermal growth factor receptor tyrosine kinase inhibitor, in A431 lung cancer cells." (PMID 19603014, 2009). "In lung cancer, PRKCSH controls cell adhesion molecules (CAMs), which are essential for T-cell surveillance,], stabilizes the insulin-like growth factor 1 receptor (IGF1R), and increases resistance to tumor necrosis factor superfamily (TNFSF)-induced apoptosis." (PMID 41350724, 2025). "Moreover, genes KDM5D, UTY, and NF1 have demonstrated gender differences in lung cancer, while PPP6C and IGF1R exhibit sex-biased expression in melanoma, and the NRAS gene may play sex-specific roles in acute myelogenous leukemia." (PMID 39541191, 2024). "Lung cancer cells treated with 2-deoxyglucose show a significant decrease in cell viability, and this cytotoxicity may be closely related to the lung cancer genes LKB1 and IGF1R." (PMID 39744129, 2024). "Notably, IGF-1R signaling has also been demonstrated to regulate the cancer stemness in various cancer stem cell (CSC) models, involving colorectal, breast, liver and lung cancers." (PMID 36233084, 2022). "In conclusion, our results corroborate the hypothesis that combination ALK and IGF-1R inhibition overcomes primary crizotinib resistance in ALK+ lung cancer cells, but does not necessarily overcome acquired crizotinib resistance." (PMID 29066738, 2017). "The use of IGF-1R-targeted therapy is no longer under investigation in lung cancer." (PMID 26793618, 2015). "The authors also reported on 6 NRAS mutant lung carcinoma cell lines and their sensitivity to the MEK inhibitors selumetinib and trametinib and their resistance to erlotinib (EGFR-TK inhibitor), crizotinib (ALK/MET/RON/ROS1 inhibitor) and linsitinib (IGF-1R inhibitor)." (PMID 25277205, 2014). "However, recent clinical trials showed that anti-IGF1R antibody and chemotherapy are not effective for treating lung cancer." (PMID 22438913, 2012). "Indeed, PRKCSH mRNA levels are not correlated with IGF1R mRNA levels in lung cancer." (PMID 38200153, 2024). "Consequently, therapeutic strategies targeting the IGF axis, such as IGF-1R inhibition by OSI-906, brigatinib, and osimertinib, have shown promising efficacy and could have an important anti-tumoral potential in lung cancer." (PMID 36902237, 2023). "The lung cancer cells (H596), exhibited no significant reduction in survival when treated with Erbitux, mAb IL6 or mAb IGF1R in monoculture." (PMID 26053043, 2015).
lung cancer (continued). "Extrinsic differences independent of the IGF-1R pathway, such as her2/neu or EGFR activation for breast or lung cancer, respectively, likely play a larger role since those pathways often serve as the primary regulator of their malignant phenotype." (PMID 24212944, 2011). "Then, we analyzed the relationship between expression of these two genes and survival in lung cancer patient, revealing that survival was correlated with expression of BCL2L1 (HR (95%CI) = 1.75(1.33–2.30)) but not correlated with expression of IGF1R (HR (95%CI) = 1.15(0.98–1.36))." (PMID 30497474, 2018). "Furthermore, SALL4 knockdown also inactivated the IGF1R/EGFR downstream intermediate target AKT, as seen from downregulation of phospho-AKT, but not MAPK in the four lung cancer cell lines examined." (PMID 27705911, 2016).